TET1 (tet methylcytosine dioxygenase 1)
Diseases named in the same sentence as TET1 in open-access papers (continued):
Sharing a sentence is not in itself a finding about the gene and the disease.
parathyroid tumor (2 papers, 2016 to 2018). "Overall, these results strongly support a growth regulatory role of TET1 in parathyroid tumor cells." (PMID 26973719, 2016). "Our novel findings also include an association of a more aberrant immunohistochemical staining pattern of 5hmC and TET1 to tumor weight for the PAs and a direct demonstration in vitro of a growth regulatory role for TET1 in parathyroid tumor cells." (PMID 26973719, 2016). "Here, we have for the first time determined levels of 5hmC and TET1 in PAs and PCs and investigated whether TET1 could play a role in parathyroid tumor cell growth regulation." (PMID 26973719, 2016). "Overexpression of TET1 in a colony forming assay inhibited parathyroid tumor cell growth." (PMID 26973719, 2016). "Consistently, overexpression of TET1 resulted in inhibition of parathyroid tumor cell growth." (PMID 26973719, 2016). "In order to test experimentally whether TET1 could interfere with parathyroid cellular growth, the parathyroid tumor cell line sHPT-1 and also HEK293T cells were transfected with a TET1 expression vector or empty vector in a colony formation assay." (PMID 26973719, 2016).
periodontitis (2 papers, 2014 to 2017). An acute or chronic inflammatory process that affects the tissues that surround and support the teeth. "A significant up-regulation of DNMT1 and TET1 mRNA was found in periodontitis patients compared to healthy controls." (PMID 29201597, 2017). "We have detected a significant upregulation in the mRNA levels of enzymes that modify chromatin, DNMT1 and TET1, in the periodontitis tissue samples (data not shown)." (PMID 25147584, 2014).
polycystic ovarian syndrome (2 papers, 2023 to 2025). "Lastly, in polycystic ovarian syndrome (PCOS) patients with GnRH neuron hyperactivity, Tet1 was hypomethylated (over-expressed), further suggesting the importance of DNA methylation in controlling GnRH promoter activity and possibly maintaining GnRH neuronal identity." (PMID 37181038, 2023).
renal fibrosis (2 papers, 2023 to 2025). A final common manifestation of a wide variety of chronic kidney diseases characterized by glomerulosclerosis and tubulointerstitial fibrosis. "Sirius red staining and immunohistochemical staining for α-SMA all demonstrated increased renal fibrosis in WT mice, which was further increased in Tet1 KO female mice at I/R 21D." (PMID 37908721, 2023).
steatosis (2 papers, 2020 to 2025). Increased lipid within the cytoplasm of cells. "Compared with the control group, the mRNA and protein levels of TET1 in the two steatosis cell lines were significantly decreased, while the mRNAs of TET2 and TET3 were not significantly changed." (PMID 32577122, 2020).
Stroke (2 papers, 2011 to 2022). Sudden impairment of blood flow to a part of the brain due to occlusion or rupture of an artery to the brain. "Therefore, to promote neurogenesis after stroke, regulation of DNA methylation by modulating TET1 expression can be considered a potential therapeutic mechanism." (PMID 36142283, 2022). "Demethylation by TET1, TET3, and Gadd45b controls the expression of galanin, Ng2, bdnf, fgf-1, RAG, and Bdnf IV in the neurorepair mechanism in stroke." (PMID 36142283, 2022).
synovial sarcoma (2 papers, 2024 to 2025). "We first investigated whether the genes that regulate DNA methylation (DNMT1, DNMT3A, DNMT3B, TET1, TET2, TET3) are misexpressed, mutated, or amplified in synovial sarcoma." (PMID 40299558, 2025). "This corroborates recent findings showing elevated expression of TET1 in human and murine synovial sarcoma when compared with normal cell counterparts." (PMID 40299558, 2025).
teratoma (2 papers, 2019 to 2020). A non-seminomatous germ cell tumor characterized by the presence of various tissues which correspond to the different germinal layers (endoderm, mesoderm, and ectoderm). "Finally, Tet1 and 2 knockout ESCs show developmental defects when injected in mouse blastocyst, and Tet1-depleted ESCs form aggressive teratomas in immunocompromised mice, which are mainly composed by endoderm, and trophoblastic giant cells." (PMID 34968225, 2019). "However, TET1 deficiency did not prevent the formation of neural tube-like structures in teratomas." (PMID 32587369, 2020).
viral infection (2 papers, 2019 to 2022). "We showed that loss of Tet1 transcriptionally mimics viral infection responses in mouse lungs and in human bronchial epithelial cells, which may promote the release of dsDNA and therefore contribute to an exacerbated IFN response." (PMID 31089182, 2019). "Moreover, whether Tet1-mediated gene regulation would explain the interplay between viral infection and HDM-induced responses in airway epithelial cells and mouse lungs will be investigated in future studies." (PMID 31089182, 2019).
airway allergy (1 paper, 2019). "Interestingly, Irf7−/− and Ifnar2−/− (deficient for type I IFN receptor) mice displayed normal dendritic cell development and allergic airway sensitization in response to HDM81, suggesting independence between type I IFN signaling and HDM-induced airway allergy when Tet1 is present." (PMID 31089182, 2019).
allergic disease (1 paper, 2023). An immune response that occurs following re-exposure to an innocuous antigen, and that requires the presence of existing antibodies against that antigen. "Prior studies on the association between TET1 and allergic disease and exposures focused primarily on how TET1 regulates DNA methylation." (PMID 38168374, 2023).
Autoimmunity (1 paper, 2021). The occurrence of an immune reaction against the organism's own cells or tissues. "Soon after weaning, at 3–4 weeks, a period of time that has been associated with the initiation of autoimmunity, we found a modest increase in expression of Tet1 but substantially increased expression of Tet2 in whole islets in NOD mice but not immune-deficient NOD/scid mice of the same age." (PMID 34417463, 2021).
bladder tumor (1 paper, 2020). "In conclusion, our study demonstrated for the first time that TET1 may function as a tumor suppressor gene in UBC and AJAP1 plays a crucial role in TET1 suppression of bladder tumor growth through modulation of the Wnt/β-catenin signaling, affecting its downstream target genes." (PMID 32528872, 2020).
breast adenocarcinoma (1 paper, 2022). "Based on these findings, we first addressed differences in TET1 isoforms and cytosine modification levels between MCF7 human breast adenocarcinoma cells and MCF10a non-transformed human breast epithelial cells." (PMID 36056023, 2022).
Burkitt lymphoma (1 paper, 2019). A rare form of malignant mature B-cell non-Hodgkin lymphoma. "We conclude that high TET1 and low TET2 expression levels in mouse T-ALL and human Burkitt lymphoma-like cells are directly MYC-dependent and are inversed upon MYC inactivation." (PMID 31266538, 2019). "Together, these results indicate that TET1 expression is high, while TET2 is low in T-ALL derived from EμSRα-tTAα;tet-o-MYC and in human Burkitt lymphoma, revealing a direct correlation between MYC and TET1, and an inverse correlation between MYC and TET2 expression levels." (PMID 31266538, 2019).
cartilaginous tumours (1 paper, 2017). "Our aim was to evaluate the effect of IDH mutations on histone modifications, DNA modifications, chromatin remodeling, and subcellular localization of TET1 in a cohort of central cartilaginous tumours with known IDH mutation status." (PMID 28484589, 2017).
cephalocele (1 paper, 2016). A congenital neural tube closure defect resulting in the protrusion of the brain through a skull opening. "The presence of a lipomatous cephalocele in Tet1/Tet2 double knockouts was not reported." (PMID 26989192, 2016).
chronic gastritis (1 paper, 2015). Inflammation of the stomach that is chronic in nature. "To determine the methylation status at the TET1 3′-shore during gastric carcinogenesis, we performed MethyLight analysis of 179 formalin-fixed paraffin-embedded (FFPE) samples of various types of gastric lesions, including chronic gastritis (CG, without IM), IM, gastric adenoma (GA), and GC." (PMID 26462176, 2015).
cocaine addiction (1 paper, 2015). "It is also important to note that several recent studies, including seminal work by Feng, Nestler, and colleagues have investigated the role of Tet1 and 5-hydroxymethylcytosine (5-hmc) cocaine addiction using animal models." (PMID 26473933, 2015).
colitis (1 paper, 2019). Inflammation of the colon. "To further assess the role of Tet1 and Tet2 in immunomodulation by PDLSCs, we compared the immunotherapeutic effects of control and Tet1/Tet2 siRNA-treated PDLSCs in experimental colitis mice." (PMID 31611558, 2019). "Tet1 and Tet2 deficiency enhance PDLSC-induced T cell apoptosis and ameliorate the disease phenotype in colitis mice." (PMID 31611558, 2019). "On day 3, colitis mice were treated with Tet1/Tet2 siRNA-treated PDLSCs or control PDLSCs by systemic transplantation through tail vein, followed by sacrifice of the mice on day 10 to collect samples for evaluation." (PMID 31611558, 2019). "Tet1 and Tet2 deficiency enhances PDLSC-induced T cell apoptosis and ameliorates the disease phenotype in colitis mice." (PMID 31611558, 2019). "Importantly, when PDLSCs were systematically infused into DSS-induced colitis mice, Tet1/Tet2-downregulated PDLSCs showed significantly increased therapeutic effects." (PMID 31611558, 2019).
colon adenocarcinoma (1 paper, 2022). "The prognosis, predictive markers, immune characteristics, mutation number of DNA damage repair (DDR) pathways, pathway enrichment, and drug sensitivity conditions were all compared between TET1-mutated and wild-type patients with colon adenocarcinoma (COAD)." (PMID 35395805, 2022). "In this study, we comprehensively characterized the landscape of TET1 mutations in ICI-treated and non-ICI-treated colon adenocarcinoma (COAD) cohorts and then compared the copy number variants (CNVs) and prognosis between TET1-mutated and wild-type patients." (PMID 35395805, 2022).
colorectal polyps (1 paper, 2024). "We utilized qRT-PCR to measure miR-200, miR-494, TET1, and Wnt1 mRNA levels in colorectal polyps, actual colorectal tumors, and normal adjacent tissues." (PMID 39495308, 2024). "This study aimed to evaluate the expression level of selective miRNAs (miR-200 and miR-494), TET1, and Wnt1 in colorectal polyps, actual colorectal tumors, and normal adjacent tissues." (PMID 39495308, 2024).
congenital malformations (1 paper, 2025). "Together with a case of NTD also observed among FA-deprived B6-Tet1 KO embryos, these data suggest that Tet1 haploinsufficiency can contribute to increased susceptibility to NTDs and other congenital malformations under conditions of maternal FA deficiency." (PMID 39578553, 2025).
diabetic eye disease (1 paper, 2025). A group of disorders affecting the eye in patients with diabetes mellitus. "Other studies, such as those on TET1 in diabetic eye disease, show that such methods can be useful." (PMID 41378129, 2025).
Down syndrome (1 paper, 2016). "Moreover, aberrant methylation of the TET1 CGI 3′-shore was also observed in persons affected by Down Syndrome, a disease with several characteristics of accelerated aging, but no information about the transcriptional outcome of this event is available yet." (PMID 27587280, 2016).
embryonic carcinoma (1 paper, 2014). "We depleted TET1, TET2, and TET3 in a pluripotent embryonic carcinoma cell model and examined the impact on genome-wide 5mC, 5hmC, and transcriptional patterns." (PMID 24958354, 2014).
Encephalocele (1 paper, 2019). A neural tube defect characterized by sac-like protrusions of the brain and the membranes that cover it through openings in the skull. "To date, only two convincing mice with genetically determined encephalocele have been described: the tuft mouse, which involves a mutation of the Tet1 gene, and the fog mutant in which the Apaf1 gene is mutated." (PMID 31628096, 2019).
epilepsy (1 paper, 2022). A brain disorder characterized by episodes of abnormally increased neuronal discharge resulting in transient episodes of sensory or motor neurological dysfunction, or psychic dysfunction. "However, in both epilepsy patients and controls, TET1 showed a relatively weak immunosignal in the endothelium." (PMID 35235761, 2022).
esophageal SCC (1 paper, 2017). "It was recently reported that TET2 expression is lower in esophageal SCC than in normal epithelium and associated with 5-hmC expression; it was speculated that TET2 is more significant in esophageal SCC development than TET1 and TET3." (PMID 28616099, 2017).
folate deficiency (1 paper, 2022). A nutritional condition produced by a deficiency of FOLIC ACID in the diet. "Taken together, these results suggested that Tet1 levels were increased concomitantly with a positive correlation to Shh gene expression in folate deficiency-induced mouse NTDs." (PMID 36199572, 2022).
germ cell cancers (1 paper, 2013). "A meta-analysis of gene expression data of germ cell cancer tissues and corresponding cell lines demonstrates high expression of TET1 and the DNA glycosylase TDG, suggesting that germ cell cancers utilize the oxidation pathway for active DNA demethylation." (PMID 24386123, 2013).
Granuloma (1 paper, 2020). A compact, organized collection of mature mononuclear phagocytes, which may be but is not necessarily accompanied by accessory features such as necrosis. "Correlation analysis among the expression of TET1, 2 and 3 and DNMT1, 3A and 3B indicated that there was a negative correlation between DNMT1 and TET3 gene expression and granuloma number in EBi3-/-I." (PMID 32078636, 2020). "Expression levels of the DNMT3A, B and TET1 and 2 genes did not correlate with number and volume of granulomas." (PMID 32078636, 2020).
head and neck cancer (1 paper, 2019). A primary or metastatic malignant neoplasm affecting the head and neck. "Epigenetic downregulation of TET1, observed in OSCC-GB patients, was earlier found associated with head and neck cancer." (PMID 31796082, 2019).
heart failure (1 paper, 2026). Inability of the heart to pump blood at an adequate rate to meet tissue metabolic requirements. "We investigated how statin therapy relates to TET1, TET2 and TET3 expression in circulating immune cells in heart failure with reduced ejection fraction (HFrEF)." (PMID 42193073, 2026).
hyperthyroidism (1 paper, 2025). Overactivity of the thyroid gland resulting in overproduction of thyroid hormone and increased metabolic rate. "Further studies showed that elevated miR-29c-3p in serum exosomes enhanced thyroid function by targeting TET1, which may be one of the causes of hyperthyroidism." (PMID 41152554, 2025). "Thus, the discovery that thyroid-specific Tet1 knockout causes hyperthyroidism will be a meaningful extension for the role of TET1 in metabolic diseases." (PMID 41152554, 2025). "Thus, TET1 inactivation may be a potential cause of hyperthyroidism." (PMID 41152554, 2025). "IHC staining showed that the thyroid follicular epithelium exhibited papillary hyperplasia in thyroid tissues from patients with hyperthyroidism, accompanied by decreased expression of TET1 compared with the controls." (PMID 41152554, 2025). "To validate this, we first intersected the upregulated miRNAs in the serum of patients with hyperthyroidism, with miRNAs potentially targeting TET1 that were predicted by miRbase and TargetScan online websites." (PMID 41152554, 2025). "In the present study, compared with Thy-Tet1+/+ mice, Thy-Tet1−/− mice developed hyperthyroidism, accompanied by elevated levels of PAX8, TPO and NIS." (PMID 41152554, 2025). "This study suggests that TET1 plays a crucial role in regulating thyroid function and that its absence can lead to hyperthyroidism." (PMID 41152554, 2025). "Thus, this study uncovers a new mechanism by which TET1 suppresses thyroid function, providing a new perspective to explore the pathogenesis of hyperthyroidism." (PMID 41152554, 2025). "Moreover, we also demonstrated that TET1 was significantly downregulated in thyroid tissues from patients with hyperthyroidism compared with healthy controls, suggesting that TET1 negatively regulates thyroid function." (PMID 41152554, 2025).
ischemic disease (1 paper, 2024). Lack of blood supply to an area of the body, resulting in impairment of tissue oxygenation. "Studies on TET1 and TET3 in angiogenesis are mainly concentrated in cancer and ischemic diseases, and its research in diabetic complications, especially DR, is scarce." (PMID 38172938, 2024).
kidney cancer (1 paper, 2020). Primary or metastatic malignant neoplasm involving the kidney. "Although TET1 did not exert a demethylation effect on OCT2, 5-hmC loss in kidney cancer has been reported to be associated with the downregulation of IDH138 and VHL39." (PMID 32206108, 2020).
laryngeal squamous cell carcinoma (1 paper, 2020). A squamous cell carcinoma that arises from the larynx. "Decreased expression of TET-1 gene occurs also in laryngeal squamous cell carcinoma (LSCC) and is connected with a lower level of 5-hmC, suggesting that the level of 5-hmC is strongly correlated with the level of TET-1 and may be a poor prognostic factor of LSCC patients in an early stage of cancer." (PMID 31712935, 2020).
lentivirus infection (1 paper, 2023). Virus diseases caused by the Lentivirus genus. "We suppressed Tet1 expression by using shTet1 lentivirus infection." (PMID 37363169, 2023).
liver fibrosis (1 paper, 2021). "By using a Tet1 hypomorphic mouse, we found that TET1 reduced levels impaired cholangiocyte proliferation after acute DDC treatment (5 days) and resulted in liver fibrosis after prolonged DDC-mediated liver injury (∼8 weeks including off-treatment intervals)." (PMID 33732709, 2021).
low grade glioma (1 paper, 2020). A grade I or grade II glioma arising from the central nervous system. "We further found that the relationship was strongest between TET1 expression and survival in low-grade gliomas." (PMID 32483272, 2020).
lupus (1 paper, 2023). "There was a significantly elevated expression of Dnmt1 and Dnmt3b, as well as Tet1 and Tet2, in CD4+ T cells of three different lupus-prone mouse strains compared to controls." (PMID 38153351, 2023). "Further, we demonstrated the upregulation of Tet1, Tet2, and Tet3 genes in CD4+ T cells of other two lupus strains, B6/lpr and B6.sle123." (PMID 38153351, 2023).
malignant glioma (1 paper, 2021). A grade III or grade IV glioma arising from the central nervous system. "Our work provides theoretical foundation for serving TET1/Wnt axis as a new target for treatments of malignant glioma patients." (PMID 34926132, 2021).
malignant pleural mesothelioma (1 paper, 2016). A malignant neoplasm that arises from mesothelial cells in the pleura and shows a diffuse growth pattern. "However, this decrease was significant in the rat for TET1 and TET3 between preneoplastic and neoplastic cell lines, and in humans for TET2 between normal mesothelial cells (MC) and malignant pleural mesothelioma cell lines (MPM)." (PMID 27129173, 2016).
metabolic (1 paper, 2023). "We therefore expanded our hypothesis for metabolic disease-driven TNBC tumorigenesis to include hyperglycemic activation of our published TET1 CSC pathway via the physical and biochemical connection of TET1 with OGT." (PMID 37231419, 2023).
metastatic cancer (1 paper, 2021). A carcinoma which has spread from the original site of growth to another anatomic site. "Intriguingly, in metastatic cancer cells of the MLN group, significant lower DNA 5hmC levels were detected, as well as lower TET1 and TET2 expression compared to those in the MT group." (PMID 33716151, 2021).